VWF (von Willebrand factor)
Diseases named in the same sentence as VWF in open-access papers (continued):
Sharing a sentence is not in itself a finding about the gene and the disease.
infection (continued). "We next examined whether binding to VWF by microsporidia would influence the biology and potentially influence systemic infection by this organism." (PMID 34095003, 2021). "Additionally, many novel genes having DOMON, VWF, and PCaP1 domains which are specific to cell membrane were highly expressed only in Tetep post infection, suggesting their role in panicle blast resistance." (PMID 33672641, 2021). "Formation of bridge between platelets or binding with fibrinogen and binding to vWF in blood vessel might be interfered by RBIV infection." (PMID 32131541, 2020). "As a result, this air-driven microfluidic pump device enabled the analyses of staphylococcal interaction with VWF on endothelial cell surfaces under shear stress conditions and was also used to establish a pneumococcus cell culture infection model of primary endothelial cells in flow." (PMID 33015097, 2020). "In addition, results of surface plasmon resonance binding studies and cell culture infections studies in flow revealed that the pneumococcus enolase interacts with both, globular circulating VWF and with VWF strings with comparable avidity." (PMID 33015097, 2020). "In contrast, infection with both the Δvwb mutant and Newman strain resulted in gradual weight loss in vWF-deficient mice, and no tangible difference was found between these two groups." (PMID 33203754, 2020). "Infected VWF KO developed less alveolar oedema versus WT mice upon infection." (PMID 31796023, 2019). "VWF is released early into the circulation upon infection with P. falciparum infection." (PMID 31796023, 2019). "Moreover, cell culture infection analyses with primary endothelial cells characterized VWF as bridging molecule that mediates bacterial adherence to endothelial cells in a heparin-sensitive manner." (PMID 30972039, 2019). "Our fluorescence microscopic visualization results of zebrafish infections demonstrate the attachment of pneumococci at endothelial vessel walls and confirm the recruitment of endogenous zebrafish-VWF to the surface of pneumococci circulating in zebrafish larvae." (PMID 30972039, 2019). "The strong and shear flow resistant attachment of pneumococci to VWF strings generated on activated endothelium might contribute to the severe infection outcome, since the attached pathogen might be protected against mechanical clearance of the blood flow." (PMID 30972039, 2019). "Increased VWF production may be a general inflammatory response of endothelial cells that could be evoked as a result of PUUV infection." (PMID 25852676, 2015). "Work has shown that elevated plasma VWF and propeptide levels develop soon after the onset of a P falciparum parasitaemia, indicating that acute endothelial cell activation constitutes an early feature of this infection." (PMID 22125593, 2011). "Additionally, environmental and genetic factors may influence the endothelial responses to these infections, further contributing to the observed geographic variability in vWF levels." (PMID 40283058, 2025). "Infection of endothelial cells upon entry of SARS-CoV-2 via ACE receptor causes an endotheliopathy (“endotheliitis”), which is associated with a prominent increase in von Willebrand factor (VWF) and factor VIII:C (FVIII:C) levels, as reported in several small case series." (PMID 36992384, 2023). "The present report correlates with a prior study from the same province in KSA that had shown higher rates of infection in individuals with blood group O., which could be due to lower serum concentrations of von Willebrand factor (vWF) and factor VIII (FVIII) in this group." (PMID 35800382, 2022). "Thus we hypothesized that microsporidia ‘spreading’ by the dysfunctional cells may not be as efficient as by shear stress in blood and by binding with VWF for better infection or transmigration to deeper tissues." (PMID 34095003, 2021).
infection (continued). "Thus, to assess whether heparin competes with VWF binding to HUVEC and in consequence abrogates the VWF-mediated adherence mechanism, infections were also performed in the presence of 30 IU heparin." (PMID 30972039, 2019). "A rapid rise in VWF such as was seen in some non-survivors in this study, has been associated with a fall in the platelet count, a process that commences early after the onset of blood-stage infection." (PMID 26830467, 2016). "Also dramatically increased beginning on day 6 after infection was Von Willebrand factor (vWF)." (PMID 20846417, 2010). "Although statistically significant for flagelliform silk protein (100Silk) only, results of RNAi experiments suggested that putative von Willebrand factor (94Will), flagelliform silk protein (100Silk) and subolesin could play a role in pathogen infection of R. microplus male salivary glands." (PMID 20298599, 2010). "Endothelial biomarkers, including von Willebrand factor (VWF), remain elevated long after infection, consistent with sustained endothelial activation or injury." (PMID 40722944, 2025). "The transcript levels of the myeloid lineage-related genes RUNX1, vWF, ITGB3, PU.1 and GM-CSF were significantly increased by 7 days of Omicron PsV infection." (PMID 40025168, 2025). "PAI-1 and vWF responded to infection differently, showing a trend of slight upregulation in PAI-1 at 4 dpi and delayed upregulation of vWF at 16 dpi." (PMID 38474396, 2024). "Patients with severe CRS are mainly characterized by elevated serum levels of angiopoietin 2 (ANGPT2) and von Willebrand factor (VWF), and these can also be used to distinguish CRS from infection." (PMID 38923216, 2024). "This experiment revealed that there still occurs endothelial damage and increased secretion of endothelial factors such as vWF and PAI-1 4 months after infection." (PMID 38188630, 2023). "The results showed that compared with ANRIL overexpression, the Sh-ANRIL double infection increased the expression of eNOS, decreased the expression of VCAM-1 and vWF." (PMID 35906216, 2022). "Moreover, endothelial cell culture infections and intravital microscopy of bacterial mouse infection confirmed that staphylococci and pneumococci resist shear stress-mediated clearance by the blood flow by binding to VWF strings at the endothelial vessel walls." (PMID 33015097, 2020). "We performed cell culture infection studies with HUVEC and serotype 35A pneumococci, which had been pre-incubated with VWF." (PMID 30972039, 2019). "Eight plasma proteins, including APOA4, haptoglobin, MBL1, vWF, LBP, and sCD14, were affected 6 h after infection." (PMID 31803186, 2019). "In vitro, the infection of EC with JUNV resulted in reduced expression and secretion of coagulation factors, such as the prothrombotic vWF." (PMID 23337384, 2013). "Within cases only, VWF activity was higher in cases with recent infections compared to those without infection (157 IU/mL versus 121 IU/mL)." (PMID 41841261, 2026). "Conversely, P. knowlesi and mixed-species infections (e.g., P. falciparum and P. vivax) show smaller or non-significant differences in vWF levels between severity groups." (PMID 40283058, 2025). "The study’s results demonstrated a significant alteration in vWF levels in individuals with Plasmodium infections, with most studies reporting an increase in vWF levels compared to those without the infection." (PMID 40283058, 2025). "Levels of plasma markers for endotheliopathy, including von Willebrand factor (VWF) antigen, VWF propeptide, soluble thrombomodulin, and endothelial colony-forming cells, remained elevated in a cohort of patients assessed at a median of 68 days post-infection." (PMID 36899952, 2023). "Interestingly, after infection ADAMTS13; a von Willebrand factor; VWF cleaving enzyme is found to be decreased." (PMID 38077924, 2023).
infection (continued). "The authors found that some patients after COVID-19 infection had persistently elevated von Willebrand factor (VWF), factor VIII, and acute phase reactants, suggesting endotheliopathy may be longstanding after infection." (PMID 36289812, 2022). "Without VWF-pre-incubation of pneumococci, only single diplococcoid bacteria were detected 5 h after zebrafish-infection (without VWF, merge, white arrows)." (PMID 30972039, 2019). "Infection of HUVEC with PUUV did not result in increased von Willebrand factor while they produced more plasminogen activator inhibitor type-1 (PAI-1) compared to controls." (PMID 25852676, 2015). "It is possible that at this lower concentration the VWF and platelets are not needed to help eradicate infection." (PMID 25809117, 2015). "Since vWF is an acute phase reactant, the possibility of false negative results during stress or infection has been considered an issue." (PMID 24385752, 2013). "Since levels of VWF returned to normal population values following infection, inherent levels of VWF do not appear to be raised in these children." (PMID 22125593, 2011). "In previous studies of I. ricinus after B. burgdorferi infection, the von Willebrand factor was isolated from tick salivary glands and shown to be up-regulated but its possible role in infection was not studied." (PMID 20298599, 2010). "Additionally, higher levels of Von Willebrand factor (vWF) and factor VIII in group A individuals, along with the acute phase reaction induced by infection, could contribute to severe outcomes." (PMID 37927694, 2023). "This is another example of a molecule (in this case VWF) that is essential to help the host survive the early phase of an infection, but with time the molecule is no longer of benefit and in this case causes some bystander injury via NET anchoring to the vessel wall." (PMID 25809117, 2015). "A significant negative correlation was observed between VWF and ADAMTS-13 in the acute phase of infection (r = −0.0575, p = 0.020)." (PMID 37886991, 2023).
vasculopathy (16 papers, 2011 to 2025). "The epithelial dysfunction due to the underlying vasculopathy leads to increased plasma levels of von Willebrand factor and plasminogen activator inhibitor type 1, leading to a procoagulant state." (PMID 41542269, 2024). "Results from clinical studies show that increased blood vWF level predicts the risk of vascular disorders and cardiac mortality in CAPD patients." (PMID 35174782, 2022). "Laboratory markers of endothelial activation (VEGF, sICAM, vWF) were used to assess potential vasculopathy." (PMID 35160284, 2022). "Subclinical vasculopathy related to large, circulating von Willebrand factor multimers may also accelerate this cognitive decline, as evidenced in population cohorts." (PMID 37176509, 2023). "Our data demonstrate for the first time the important ability of ARC to significantly reduce endothelial cell activation and vWF release and suggest that its exploration in vasculopathies may be of particular interest." (PMID 35456570, 2022).
blood disorder (14 papers, 2014 to 2025). "Caplacizumab, with a cosine similarity score of 0.294, is approved for treating adult acquired thrombotic thrombocytopenic purpura (aTTP), a rare blood disorder caused by an autoantibody-mediated severe deficit in the von Willebrand factor (vWF) cleaving metalloproteinase ADAMTS13." (PMID 39264975, 2024). "Endothelial damage and inflammation induce upregulation of VWF in patients with hematologic malignancies as well." (PMID 41091182, 2025). "It is a 26S proteasome inhibitor, used mainly in the treatment of hematological malignancies, but also works by inhibiting the activity of ADAMTS-13 metalloproteinase, also known as von Willebrand factor (vWF) cleavage protein, contributing to improve microcirculation." (PMID 39061613, 2024).
inflammation (14 papers, 2012 to 2025). Aberrant reaction of the microcirculation characterized by movement of fluid and leukocytes from the blood into extravascular tissues. "Blockade of the aldosterone pathway by spironolactone or treatment by ProvinolsTM prevented the increase in circulating microparticles and plasma vWF as well as the associated vascular inflammation." (PMID 22808030, 2012). "Endothelial cells are also responsible for the synthesis of the von Willebrand factor (vWF), a glycoprotein synthesized in the endoplasmic reticulum of these cells, which is important in the coagulation cascade and vascular inflammation." (PMID 33525692, 2021). "Biomarkers for vascular inflammation include a high plasma level of C-reactive protein, soluble cell-adhesion molecules, von Willebrand factor, aldosterone, and proinflammatory cytokines like interleukin-6 or tumor necrosis factor α." (PMID 32408603, 2020). "vWF, a marker of vascular inflammation, increased in the placentae of obese gilts, which was consistent with the observed increase in ROS levels, suggesting that increased oxidative stress leads to vascular endothelial dysfunction." (PMID 31662816, 2019). "Interestingly, von Willebrand Factor and its regulator ADAMTS-13 have been implicated in vascular inflammation and the development of immunothrombosis, providing a potential causative link between inflammation and coagulation in SARS-CoV-2 patients." (PMID 35482749, 2022). "In addition to its hemostatic function, VWF has been shown to be involved in vascular inflammation." (PMID 37559057, 2023). "In contrast, biomarkers of endothelial inflammation (sVCAM-1, sICAM-1, sE-selectin, sP-selectin) and classical hemostasis biomarkers (PAI-1, t-PA, von Willebrand factor) displayed comparable responses to LPS in aged and young mice." (PMID 41291381, 2025).
bacterial infections (10 papers, 2017 to 2025). "The factors associated with hematoma volume and possible expansion include the use of anticoagulant medications, autoimmune or bacterial diseases that reduce platelet production, and genetic defects of Von Willebrand factor causing inhibition or reduction of platelet aggregation." (PMID 28280651, 2017). "The von Willebrand factor is a multifunctional protein in plasma that interacts with bacteria, promoting bacterial attachment and exacerbating bacterial infections." (PMID 39596793, 2024). "According to the in‐ and exclusion criteria, 690 patients were excluded because of missing information on ABO blood type (n = 643), VWF (n = 10), important clinical data (n = 37), or HCC/evidence of active bacterial infection (n = 9)." (PMID 32052552, 2020).
cardiac disease (8 papers, 2018 to 2025). "In this review, we aim to describe the associations of VWF, ADAMTS13, and cardiac disease in some detail." (PMID 34564132, 2021). "We recommend that workers in the field of cardiac disease take a greater interest in both VWF and ADAMTS13, to both identify the opposing risks of bleeding and thrombosis, and to potentially consider supportive therapies or curative approaches, as the case may require." (PMID 34564132, 2021).
genetic disorder (7 papers, 2009 to 2023). "A genetic disorder, caused by partial or total deficiency or structural aberrations of vWF molecules, is called vWD." (PMID 33096906, 2020).
adenocarcinoma (6 papers, 2008 to 2018). A common cancer characterized by the presence of malignant glandular cells. "We found abundant expression of IL-33 in the nucleus of CD31+ or vWF+ endothelial cells from blood vessels in adenocarcinomas of the kidney, stomach, liver, pancreas, lung, breast or colon (data not shown)." (PMID 18836528, 2008).
infectious disease (6 papers, 2012 to 2024). A disorder directly resulting from the presence and activity of a microbial, viral, or parasitic agent in humans. "The significant inhibitory effect of ISE on EC-associated vWF levels may also provide an interesting direction for its application to other vascular and infectious diseases in the future." (PMID 38921594, 2024). "Bacterial interaction with VWF is of high medical and scientific importance since this interaction is directly associated with specific clinical manifestations and long-term complications of infectious diseases." (PMID 33015097, 2020). "Notably, the injured endothelium is another major source of elevated circulating vWF levels, especially under diseased conditions, such as vascular and infectious diseases." (PMID 38921594, 2024). "What DHF/DSS distinguishes from these other severe infectious diseases is that consumption of VWF;Ag and loss of larger VWF multimers have not been observed in these other diseases." (PMID 22563509, 2012).
liver (6 papers, 2015 to 2023). "In fact, ALX-0081, a nanobody against the A1 domain of VWF that blocks VWF binding to GPIbα, has recently been shown to prevent middle cerebral artery (MCA) thrombosis in guinea pigs and to induce reperfusion when given immediately after complete occlusion, without provoking intracerebral bleeding." (PMID 25297919, 2015). "When GLP1 was administered (CD+GLP1+LT), it resulted in higher SOCS1 and SOCS3 expression than in the CD+LT group, and this was accompanied by less liver inflammation, evidenced by decreased levels of liver MPO, MDA, NO production, nitrotyrosine, and plasma vWF." (PMID 31835410, 2019).
retinopathy (6 papers, 2011 to 2025). "Moreover, we found that von Willebrand factor (VWF) is highly expressed in endothelial cells and is an important factor that aggravates vascular endothelial cell damage and promotes the development of retinopathy." (PMID 36533134, 2022).
metabolic disorders (5 papers, 2013 to 2026). "Hence, the difference in association between levels of VWF with metabolic diseases depending on whether it is within the plasma or EVs may provide important mechanistic insights and warrant further discussion and research." (PMID 36613770, 2022). "Few studies have reported high levels of vWF in patients related to metabolic disorders." (PMID 30519274, 2018). "Finally, we will mention a recently discovered pathogenetic mechansisms that can be responsible for accumulation of UL-VWF multimers and promote forms of TMAs in cardiovascular and metabolic disorders by perturbing the VWF/ADAMTS13 interaction." (PMID 24106608, 2013). "VWF and ADAMTS13 have been proposed as useful biomarkers and predictors of prognosis in patients with cardiovascular and metabolic disease." (PMID 28634421, 2017).
inflammatory myopathies (3 papers, 2015 to 2025). "In addition, angiogenesis-related pathways were enriched, and the canonical endothelial cell marker VWF was significantly elevated in ANCA-negative VM compared to other myopathies." (PMID 41441888, 2025). "Birds suffering from this myopathy exhibit down-regulation of eight hemostatic genes (A2M, FGA, FGB, FGG, KNG1, SERPINC1 and VWF) and up-regulation of four other coagulation genes (F5, F10, PROS1 and F2R)." (PMID 26445145, 2015).
autosomally inherited disorder (1 paper, 2010). "VWD is an autosomally inherited disorder resulting from a quantitative or a qualitative defect of Von Willebrand factor (VWF) affecting both genders." (PMID 20822539, 2010).
colon polyps (1 paper, 2024). "Furthermore, he experienced several episodes of gastrointestinal bleeding after polypectomy for colon polyps despite the appropriate administration of VWF/factor VIII." (PMID 38926208, 2024).
VWF also shares sentences with these, for which no sentence is quoted: portal hypertension (22 papers); acute myocardial infarction (14); thrombophilia (12); hemophilia B (8); pulmonary embolism (8); antiphospholipid syndrome (6); arteriovenous malformations (6); Iron deficiency anemia (6); type 2 von Willebrand disease (6); Bernard-Soulier syndrome (5); leukemia (5); bipolar disorder (4); cerebral infarction (4); esophageal varices (4); hyperhomocysteinemia (4); immune thrombocytopenia (4); anticoagulant (3); chronic obstructive pulmonary disease (3); deficiencies (3); Graves disease (3); Impaired glucose tolerance (3); meningioma (3); myocarditis (3); myositis (3); pulmonary disease (3); renal failure (3); respiratory disease (3); abdominal aortic aneurysm (2); acute chest syndrome (2); acute respiratory failure (2).
A further 191 diseases each share a sentence with VWF in 2 papers or fewer.